YAP1 (Yes1 associated transcriptional regulator)
Diseases named in the same sentence as YAP1 in open-access papers (continued):
Sharing a sentence is not in itself a finding about the gene and the disease.
tumor (continued). "Thus, we surmise that the effect of Yap1 inhibition may be mediated through a cancer cell–intrinsic, auto-/paracrine IL-11–dependent mechanism, which may potentially be augmented by a concomitant anti-tumor effect emanating from reduced IL-11 signalling in CD4 effector cells." (PMID 37957015, 2024). "Herein, we reveal that unlike chronic developmental Sox9 deletion, the acute and therapeutic elimination of Sox9 reduces overall cHCC-CCA tumor burden in Akt-YAP1 but not the Akt-NRAS model." (PMID 39273023, 2024). "Differences in expression pattern may reflect cell lines derived from subpopulations of YAP1- and WWTR1-expressing cells within the tumor or from culture conditions." (PMID 36719743, 2023). "Dividing the EGFR-mutant NSCLC patients into two subpopulations based on YAP1 expression, we found that patients with YAP1_High tumor had immunosuppressive immune cells and inferior prognosis in EGFR-mutant NSCLC patients compared to those with YAP1_Low tumor." (PMID 37388902, 2023). "Recently, CA3 (CIL56), YAP1/TEAD inhibition was shown to strongly inhibit esophageal adenocarcinoma cell growth and induce strong anti-tumor effects by suppressing tumor cell proliferation, and cancer stem cell phenotype in a xenograft model with no apparent toxicity." (PMID 37190141, 2023). "The KD appeared to reduce liver weight/body weight ratio and significantly suppressed tumor multiplicity and total tumor volume, reproducing the phenotype observed in the Scd2f/f;CC mice and validating the role of LTB4R2 in CTNNB1 and YAP1 activation and liver tumorigenesis in vivo." (PMID 37156770, 2023). "The reciprocal expression pattern between YAP1 and WWTR1 and the cluster 0/NE genes and the correlation with viral status was more evident in the established cell line RNA-Seq data than it was for the PDCLs or 44 tumor biopsies." (PMID 36719743, 2023). "In fact, YAP1 and IL6ST signaling pathways have a role in promoting liver tumors, and the impaired degradation of the two proteins by either the proteasome or macroautophagy has already been shown to promote tumor growth." (PMID 35435804, 2023). "The overexpression of YAP1/TAZ coactivators is common in several solid tumors by not only initiating the tumor growth but also maintaining the continued growth of the tumor." (PMID 37240355, 2023). "To verify YAP1 translocation and the upregulation of EGFR expression in preclinical models, we stained YAP1 and EGFR in tumor tissues of two patient‐derived xenografts (PDX), namely, PDX1 and PDX2, that were treated with trametinib in NSG mice and showed tumor growth delay." (PMID 37501404, 2023). "Based on preliminary data, YAP1 interaction with β-CATENIN and NANOG seems to play an important role, as removing β-CATENIN from the HBx and HBx + NANOG models decreased colony formation and tumor incidence." (PMID 37744383, 2023). "In summary, our findings identified a novel regulatory mechanism for the oncogenic function of NF1 to regulate YAP stability through direct interaction between its PPQY motif and the WW domains of YAP1, even though NF1 was traditionally considered to be a tumor suppressor in RAS-MAPK signaling." (PMID 37147639, 2023). "Tumours that are predominantly positive for MYC are in either POU2F3 or YAP1 subgroups, while MYC negative tumours are mostly in ASCL1 and NEUROD1 subtypes." (PMID 37870696, 2023). "Consequently, the phosphorylated YAP1/TAZ proteins are excluded from the nucleus and subjected to proteasomal degradation, inhibiting tumor growth." (PMID 38136274, 2023). "Additionally, accumulating studies have confirmed that the m6A demethylase ALKBH5 inhibits tumor growth, metastasis, invasion, and tumor angiogenesis in NSCLC by reducing YTHDFs-mediated YAP1 expression and inhibiting miR-107/LATS2-mediated YAP1 activity." (PMID 38053093, 2023).
tumor (continued). "By a CCK8 assay, colony formation assay, and flow cytometry, our team is the first to develop the strategy of co-targeting YAP1 and PD-L1 in SCLC, which dramatically boosted anti-tumor immunity and provided new ideas for combination therapy in patients with the SCLC-Y subtype." (PMID 37752152, 2023). "We asked whether the reciprocal expression of YAP1- and WWTR1-dependent genes and NE markers could be observed in the bulk RNA-Seq of the 44 tumor biopsies." (PMID 36719743, 2023). "YAP1 negatively regulates Smad3 expression to mediate EMT and tumor metastasis." (PMID 37996892, 2023). "Independent of Hippo pathway dysregulation, YAP1 can be activated via mechanical stress, such as stiffness of the tumor microenvironment and/or tissue adhesion." (PMID 36291755, 2022). "Except for YAP1/TAZ, the upregulation of their well-established downstream targets, such as CTGF, BIRC5, and AREG, has also been revealed to drive gastric carcinogenesis and tumor progression." (PMID 36289774, 2022). "In the present study, increased expression of phosphorylated Mst1, LATS2 and YAP1 was observed in CRC cells overexpressing MT2A, and similar results were also observed in subcutaneous CRC tumor and liver metastasis tissues overexpressing MT2A according to immunohistochemical staining." (PMID 35642057, 2022). "In NSCLC, the expression of YTHDF1 is higher in tumor tissues than in normal tissues, while the expression of YTHDF2 is lower in tumor tissues than in normal tissues, indicating that YTHDF1 is more likely to bind to methylated YAP1 mRNA to promote its translation." (PMID 35063010, 2022). "The ability of YAP1 to regulate TAZ abundance may at least partly account for the contradictory role of YAP1 and TAZ as oncogenes or tumor suppressors in different cellular contexts." (PMID 35930163, 2022). "Although recent immunohistochemistry (IHC) analyses confirmed that subtype‐specific markers are indeed detectable in human tumour tissue samples, these studies failed to distinguish a unique YAP1‐driven subtype." (PMID 36149789, 2022). "Overexpressed YAP1 induced NMU expression, which promoted tumor metastasis in vitro and in vivo." (PMID 36290882, 2022). "Our data revealed that ASCL1, NEUROD1, and POU2F3 were exclusively expressed in the malignant cells of SCLC tumors, however, YAP1 was mainly expressed in normal epithelial cells rather than tumor cells." (PMID 36195615, 2022). "To determine whether YAP1 activation by LIN28 is dependent of Let-7, we firstly analyzed the expression of Let-7g in TNBC cells, which is the most relevant Let-7 isoform with tumor metastasis and poor patient survival in BCs." (PMID 35102250, 2022). "Immunostaining confirmed that a large proportion of YAP1-positive cells also co-express the non-NE club cell marker CC10 in mouse SCLC tumor sections." (PMID 35577801, 2022). "Western blot analysis confirmed the overexpression of YAP1 and knockdown of DOCK1 in tumor tissues." (PMID 35217990, 2022). "We show that downregulation of YAP1 in a dysfunctional Hippo genetic background results in the inhibition of YAP1/TEAD-dependent gene expression, the induction of apoptosis, and the inhibition of tumor cell growth in vitro." (PMID 35689194, 2022). "In conclusion, our study reveals that OTUD1 potentially acts as a tumor suppressor and suppresses erlotinib resistance of NSCLC through the YAP1/SOX9/SPP1 axis, suggesting that OTUD1 may serve as a target for reducing chemoresistance for NSCLC." (PMID 36182943, 2022). "In TNBC models, BETi JQ1 disrupts enhancer remodeling induced by MEKi trametinib, blocks kinome reprogramming and suppresses tumor growth; in lung cancer models, JQ1 can overcome MEK and TBK1 inhibition resistance via suppressing adaptive activation of YAP1/TAZ and IGF1/IGF1R signaling." (PMID 35966590, 2022). "To determine the relevance of YAP1 in MPM, we explored the role of YAP1 on tumor maintenance and whether the selective inhibition of YAP1 could drive antitumor activity in vivo." (PMID 35689194, 2022).
tumor (continued). "Hence, based on this data, 67% TOR on TEAD1, 30–40% decrease in the YAP1-TEAD transcription score, and 60% downregulation of CYR61 protein levels are sufficient to achieve tumor regression in the MPM NCI-H226 model." (PMID 35689194, 2022). "In addition, in pancreatic cancer, YAP1 cooperates with K-RAS and induces tumour survival and EMT, which is involved in cancer cell metastasis." (PMID 35565411, 2022). "In addition, gastric epithelial cells infected with CagA-positive H. pylori have been shown to activate YAP1 and thus promote EMT and tumor growth of GC." (PMID 36289774, 2022). "Intriguingly, we identified copy number alterations (CNAs) of various oncogenes and tumor suppressors (e.g. Yap1, Braf, Foxo1, Akt3 and Rb1) in RMS tumors developing in DK mice, which might play important roles for tumor formation and growth." (PMID 36376321, 2022). "Interestingly, PAF1 and YAP1 were co-localized and co-expressed in metaplastic ducts and PDAC tumor tissues." (PMID 36180487, 2022). "However, it is worth noting that aberrant YAP1 and TAZ have recently been considered tumor suppressors in CRC in several studies." (PMID 36289774, 2022). "Importantly, we identified a novel GRK3 inhibitor, LD2, through a chemical library screen and demonstrated its strong anti-tumor activity in vitro and in vivo in patient-derived PC cells with high GRK3 and YAP1 expressions." (PMID 35996148, 2022). "YAP1 expression and tumor stiffness were only correlated in the tumors of non-collagenous stroma (Table A4)." (PMID 36291755, 2022). "In the univariate Cox proportional hazard model, negative hormone receptor status, high histologic grade, tumor size > 2 cm, and high nuclear YAP1 expression were found to be significant prognostic factors for OS." (PMID 33718163, 2021). "Furthermore, some oncogenic genes like EGFR, CDK6, YAP1, and MMP7 were amplified in the TP53INP2-low patients while some tumor suppressor genes including CDKN2A, KLF6, and PTEN were deleted." (PMID 33897760, 2021). "Both YAP1 and TAZ have also been shown to regulate the tumor immune microenvironment via numerous avenues, including tumor cell-intrinsic properties via directly regulating the expression of PD-L1, as well as recruitment of immunosuppressive cell types via induction of secreted factors." (PMID 34685695, 2021). "When YAP1 and CBX4 were modulated with CA3 and UNC3866, tumorigenicity and stem-like properties were extremely inhibited, thus indicating that these compounds exerted a strong anti-tumour effect in vivo against SR HCC cells." (PMID 33473171, 2021). "Finally, YAP1 and TAZ, downstream effector proteins of the Hippo tumor suppressor pathway, are also examples of proteins that upregulate SLC7A5 expression." (PMID 33953707, 2021). "Moreover, YAP1 was reported to induce TEAD-dependent focal adhesion kinase phosphorylation, ultimately promoting tumor invasiveness." (PMID 33718163, 2021). "Interestingly, on IF staining, the expression of CSC markers YAP1 and EpCAM was preserved in GA0825 PDX, recapitulating the expression in the corresponding donor PC cells (IP-116) and its primary tumor." (PMID 34162421, 2021). "Additionally, many published studies looking at the role of YAP1/TAZ and TEAD in regulating tumor growth rely on analyzing tumor initiation." (PMID 34685695, 2021). "YAP1 and TAZ are likely involved in this facet of tumor biology as intrinsic regulators of certain immune cell subsets as well as extrinsic regulators of the immune response via their oncogenic driver role in tumor cells." (PMID 34685695, 2021). "As YAP1 is frequently upregulated in human cancers, YAP1 is often considered to be an oncogene rather than a tumor suppressor gene." (PMID 34831091, 2021).
tumor (continued). "In brief, our findings indicate that CBX4 is essential for tumorigenesis by initiating YAP1 function in the nucleus to maintain CSC capabilities and is a good therapeutic target for preventing and treating tumours as well as evaluating the prognosis in patients with SR HCC." (PMID 33473171, 2021). "This indicates the prognostic importance of post-chemotherapy YAP1 mRNA expression and confirms YAP1 mRNA expression is not a prognostic factor in primary tumours." (PMID 34771529, 2021). "Endpoint tumour BA spheroids also exhibited this PGE2-dependency and maintained the same foetal-like phenotype in long-term culture as evidenced by LY6A expression and YAP1 nuclear localization." (PMID 34103493, 2021). "In many contexts, YAP1 is not the driver of tumor growth but rather an acquired mechanism that adds to a set of already present driver alterations and increases tumor aggressiveness or resistance to therapy." (PMID 34685695, 2021). "Moreover, modulation of the core stem genes has been analyzed, providing evidence of the involvement of the tumor suppressor genes MEN1 and YAP1 and of WNT/β-catenin signaling." (PMID 34199594, 2021). "In addition, YAP1 enhances p73-dependant apoptosis in response to DNA damage in NSCLC 40, 41, and represents a pharmacological target to enhance the anti-tumour effects of DNA-damaging modalities for urothelial cell carcinoma treatment." (PMID 33613118, 2021). "More significantly, collagen/fibronectin could facilitate the activation of PI3K/AKT/SOX2 and CDC42/YAP-1/NUPR1/Nestin signaling pathways via integrin αvβ3, eliciting sustained tumor growth and cancer relapse." (PMID 33408794, 2021). "It is therefore conceivable that the tumor-promoting or cancer suppressive functions of YAP1 might be dependent on the presence of RASSF1A, and that RASSF1A modulates the function of YAP1 such that it acts as a tumor suppressor." (PMID 34831091, 2021). "Tumor HMGB1 and TLR4/RAGE receptors promote cell proliferation, survival, migration, epithelial-to-mesenchymal transition, and apoptosis resistance involving interaction with β-catenin, Runx2, YAP1, and TGF-β1/Smad." (PMID 33669632, 2021). "Within the primary tumours, YAP1 mRNA expression levels were not a significant prognostic factor with (p = 0.66) or without (p = 0.072) chemotherapy treatment." (PMID 34771529, 2021). "The tumor tissue samples were collected from CMM patients, and we constructed a CMM animal model with PLX 4032 resistance to analyze the effect of UMMD treatment on YAP1 expression in vivo." (PMID 33996543, 2021). "Analyses of YAP1 subcellular distribution in tissue sections of +DDR/+COL1 tumours by IHC, however, failed to reveal a clear-cut increase in nuclear over cytoplasmic YAP1 localization when compared to −DDR/+COL1 (not shown)." (PMID 32047176, 2020). "We found that all LATS1/2 cKO animals where one or both copies of YAP1 was deleted still exhibited tumours at P20 (n = 3 each), indicating that YAP1 is not the sole downstream factor regulated by LATS1/2." (PMID 32404936, 2020). "Our results suggested that activation YAP1 dependent immune regulatory network may enhance the activity of resting CD4+T cells, thereby promoting tumor progression in PC." (PMID 33123286, 2020). "On the other hand, the tumor-forming potential of both fusions was observed when expressed in neonatal brains using the RCAS/tv-a system, thus suggesting a potentially different tumorigenic mechanism between these YAP1 fusion genes." (PMID 33228790, 2020). "Since cell contact is constantly changing during tumor proliferation and progression, as is likely the level and intracellular localization of YAP1, we next seeded cells at very LCD to derive single cell clones before immunofluorescence staining for YAP1." (PMID 32292505, 2020). "In addition, YAP1 can increase and sustain HIF1A protein stability, thereby establishing a HIF1A/YAP1 positive feedback loop that mediates Nic-stimulated EMT and tumor progression in PDAC." (PMID 32894161, 2020).
tumor (continued). "Although the ARID1A–SWI/SNF complex is inactive during tumor growth, this negative association highlights the role of the ARID1A–SWI/SNF complex in cancer development through the suppression of oncogenic YAP1/TAZ activity." (PMID 32390875, 2020). "To investigate the role of YAP1 in the MDR of SCLC in vivo, we constructed tumor xenograft models." (PMID 31692299, 2020). "According to previous investigations and bioinformatics predictions, HIF1A could promote tumour glycolysis, and its promoter region might have a DNA binding motif for TEAD1, a transcription coactivator of YAP1." (PMID 33218358, 2020). "The non-sRCCs were predominantly higher risk tumours; only 14 of the 268 (5%) had Hippo pathway alterations, involving NF2 (6/268), FAT1 (3/268), LATS1 (2/268), LATS2 (3/268) and YAP1 (1/268)." (PMID 31959902, 2020). "Immunoblot analyses of the ±DDR/−COL1 tumours revealed that neither DDR1b nor DDR2 expression altered the levels of either YAP1 and its phosphorylated forms, MST1 and MST2, LATS1 or KIBRA, when compared to tumours with repressed DDRs (+DOX)." (PMID 32047176, 2020). "Although all underlying mechanisms are not clearly determined, it is evident that activating YAP1 pathways in different cellular components induces an immunosuppressive tumor microenvironment." (PMID 31963556, 2020). "When activated, YAP1 localizes to the nucleus and binds to transcription factors, such as TEA domain DNA-binding family of transcription factors (TEAD), and then drives tumor growth, metastasis, and senescence in cancer cell lines and induces the EMT in many types of tumors." (PMID 32728069, 2020). "In a thorough study of the tumorigenic capacity of 14 different mutant forms of CTNNB1 with Yap-1, Zhang and colleagues showed that specific mutant forms of CTNNB1 determine HB tumor growth rates, survival, histologic features, metabolic features, and transcriptional profiles." (PMID 31979130, 2020). "The YAP1/TEAD1 protein complex had the capability to influence downstream cytoskeletal proteins by regulating SRC transcription; therefore, it converts NF to CAF, and CAF can significantly promote tumour growth and metastasis." (PMID 32066485, 2020). "Also, YAP1 can interact with ZEB1 in the EMT process, which favors tumor progression and metastasis in WT." (PMID 32766179, 2020). "YAP1-mediated PKM2 expression enhances cell glycolysis and adapts tumor cells for abnormal growth." (PMID 32390875, 2020). "Nuclear expression of YAP1 in MLS specimens did not correlate with clinical characteristics such as patient age, gender, FUS‐DDIT3 transcript variant, or tumor size." (PMID 30898787, 2019). "There have been studies reporting that the interaction between KRAS and YAP1 could regulate EMT and tumor survival." (PMID 31827075, 2019). "Clinicopathological and biological analyses suggest that the expression of YAP1 target genes is correlated with tumor progression in non-small cell lung cancer, triple-negative breast cancer, and colorectal carcinoma." (PMID 31575084, 2019). "Different from non-tumorous tissues, the reciprocal interaction of YAP1 and substrate rigidity induces genetic, epigenetic and phenotypic changes during tumor progression." (PMID 30934860, 2019). "A consistent correlation of YAP1/TAZ expression with clinical parameters including tumor progression was not feasible in this cohort." (PMID 31873172, 2019). "YAP1 overexpression induced NMU expression and transcription and promoted cell motility in vitro and tumor metastasis in vivo via upregulation of epithelial–mesenchymal transition (EMT), whereas specific inhibition of NMU in cells stably expressing YAP1 had the opposite effect in vitro and in vivo." (PMID 31575084, 2019). "The selected candidate biomarkers were then validated on HNSCC patient tissue specimens by RT-qPCR which provided quantitative data on expression of these selected genes (relative to two reference genes YAP1 and POLR2A) on paired margin and tumour core tissue samples." (PMID 31443700, 2019).